AR (androgen receptor)
Diseases named in the same sentence as AR in open-access papers (continued):
Sharing a sentence is not in itself a finding about the gene and the disease.
tumor (continued). "The most important finding was that in the castration-resistant tumor the AR remains the key regulator and driver of tumor growth, spread and survival and the most promising therapeutic target." (PMID 23792785, 2013). "It has been reported that liver tumour tissues have significantly higher levels of AR than tumour-adjacent tissues." (PMID 23883094, 2013). "While upregulation of the AR-target gene p21WAF1 promoted tumor cell proliferation through the MAPK pathway, hyperactivation of MAPK by concurrent AR and EGFR-signaling pathways caused tumor growth suppression." (PMID 24324894, 2013). "Consistently, the tumor antigens simian virus 40 small t antigen (ST) can mediate PP2A (phosphoprotein phosphatase 2A) binding to AR, leading to AR dephosphorylation at five Pro-directed phosphoserines in the NTD and reduction in AR activities." (PMID 25866551, 2013). "In hormone-naïve patients, withdrawal of androgen by surgical or chemical castration or by antiandrogens blocks AR stimulation and results in massive induction of apoptosis and tumor shrinkage." (PMID 23792785, 2013). "Mice bearing AR-independent PC3 xenograft tumors treated on this schedule exhibited a significant decrease in tumor volume compared to control animals (T/C value 17%)." (PMID 23152004, 2013). "Since AR is frequently expressed in ERBB2 amplified tumors, we asked how the loss of AR signaling would affect tumor incidence and progression in this cohort." (PMID 23593223, 2013). "While being counterintuitive, there is considerable evidence that for most CRPC patients androgen receptor (AR) signaling is still required for tumor growth." (PMID 23781155, 2013). "The management of hormone-refractory prostate cancer represents a major challenge in the therapy of this tumor, and identification of novel androgen receptor antagonists is needed to render treatment more effective." (PMID 23667504, 2013). "But an opposite response is triggered in tumor cells, where both proliferation and survival depends on AR." (PMID 24199173, 2013). "A typical nuclear staining pattern of AR appears in tumor cells of intact mice, and in contrast a diffuse and cytoplasmic staining pattern of AR in castrated mice." (PMID 23308230, 2013). "ERG expression beyond a certain threshold would convey castration resistance to the tumor cells, which in turn increases the AR copy number and expression to compensate for androgen deprivation, contributing to disease progression and metastasis." (PMID 24098661, 2013). "Some authors demonstrated that AR are expressed in 80% of invasive breast cancers, but only in 21% of all ER-ve tumours." (PMID 23816265, 2013). "The ability of physiological concentrations of genistein to activate tumor derived AR was considerably conserved across other mutant ARs." (PMID 24167630, 2013). "Our findings also support a new role of AR silencing via siAR in mediating the induction of EMT via CCL2-STAT3 activation in the tumour microenvironment." (PMID 23982944, 2013). "Linear mixed models predicted AR copy number at the cell level by tumor type, with random patient effects." (PMID 24098661, 2013). "We next examined the expression of c-jun, p-cjun, AR and Ki67 proteins in the tumor tissues harvested to assess the effect of drug treatment." (PMID 24260253, 2013). "HRPCa-2, a parent tumor, expressed classic secretory cell markers including cytoplasmic K18, nuclear AR, and cytoplasmic PSA." (PMID 23985008, 2013). "PSA secretion is a sensitive indicator for androgen receptor (AR) signaling activity in AR-dependent tumor cells." (PMID 23724038, 2013). "We found that miR-200b was significantly upregulated in the poorly tumorigenic PC3 AR-positive cells and that overexpression of miR-200b led to decreased tumor growth." (PMID 24391862, 2013). "Nuclear expression of p44 is decreased in PCa and overexpression of nuclear p44 caused growth arrest both in in vitro cell proliferation and in vivo tumor xenografts in an AR-dependent manner." (PMID 23734213, 2013).
tumor (continued). "In HPCa70 patient tumor, most tumor cells were highly positive for luminal markers AR, PSA, CK8, and racemase but weakly positive for CK5 and negative for p63." (PMID 23451107, 2013). "A non-invasive, imaging-based biomarker to address the issue of aggressiveness, metastatic tumor burden, and degree of AR signaling activity would be a tremendous advance to improving risk stratification and therapeutic monitoring of cancer patients." (PMID 23863691, 2013). "The low number of tumor-bearing mice during the course of this study prevented further evaluation of the role of AR deletion in MMTV-NeuNT male mice." (PMID 23593223, 2013). "In vivo, long-term enzalutamide or ARN-509 therapy in mice bearing LNCaP/AR xenograft tumors also resulted in the outgrowth of tumor cell populations expressing AR F876L." (PMID 23580326, 2013). "TUNEL assay also showed the orthotopic TRAMP-C1 siAR tumours + CCR2atg had the highest number of apoptotic cells, suggesting that both AR and CCL2 pathways are essential signals for PCa tumourigenesis." (PMID 23982944, 2013). "We also showed that c-Myc overexpression attenuated the anti-tumor activity of AR suppression with RNAi." (PMID 23704919, 2013). "A chemotherapy agent such as BA that can specifically degrade AR and cyclin D1 is especially important in PC therapy due to the importance of these proteins in tumor progression." (PMID 23424652, 2013). "Our group established a patient-derived tumor graft line that expressed AR Trp741Cys that recapitulated AWS and effectiveness of alternative anti-androgen therapy in vivo." (PMID 23896594, 2013). "Through their collaborative effort, AR and β-catenin were directly linked to androgen-induced HER3 expression and, indirectly, to the pernicious tumor characteristics imparted by the HER2/HER3 heterodimer." (PMID 24324894, 2013). "These antiandrogens have a low affinity for the AR and can lose their AR inhibitory property or even become AR agonists in castration-resistant tumor cells." (PMID 23792785, 2013). "PCa CTCs are reported to reflect those mutations present in the primary tumor e.g., TMPRSS2-ERG fusions, androgen receptor mutations, and PTEN deletion which, together with PSA, AMACR and androgen receptors, can predict the response to treatment." (PMID 23708103, 2013). "Low levels of AR mRNA or AR protein is detectable in AR-negative tumor cell lines, suggesting AR expression is sensitive to both mRNA and protein stability factors." (PMID 24199173, 2013). "The factor 1 (SATB1/HIF-1α-AR/ER/BCL2) pattern in the HR-positive tumours revealed an inverse relation between the two groups of markers with the opposite factor loadings." (PMID 22424533, 2012). "The existence of AR–VE cancer stem cells has been postulated as a mechanism by which tumours relapse by overcoming androgen ablative therapies that target AR+VE cells." (PMID 23145034, 2012). "Immunohistochemical analysis shows that tumor sections from the kava extract or flavokawain B treated PCa xenografts exhibited a significant decrease in both density and the number of positive AR staining cells compared to those of vehicle control treatments." (PMID 22347450, 2012). "The mRNA and protein levels of AR and Kitl were analyzed in cultured mouse granulosa cells and a steroidogenic human ovarian granulosa-like tumor cell line, KGN, after overexpression and knockdown of Nur77 in vitro." (PMID 22761936, 2012). "The decrease and delay in castration-recurrent tumor growth, coupled with a 36% extension of survival in the presence of T, supported the importance of inhibition of AR expression/activity as a clinical target." (PMID 22272301, 2012). "Upon emergence of CRPC, the aneuploid and diploid tumor cell populations both displayed AR amplification but with dramatically different patterns." (PMID 22956944, 2012). "Remarkably, the aneuploid tumor cell population, which displayed the highest AR copy number, disappeared following treatment with bicalutamide." (PMID 22956944, 2012).
tumor (continued). "The results suggest that intratumoral T and DHT synthesis induces dominant negative ARΔTR inhibition AR dependent CWR-R1 tumor growth." (PMID 22272301, 2012). "This was particularly informative, because it demonstrated that cell populations with differing degrees of AR amplification existed within a single tumor and that these populations appeared to respond differently to orchiectomy versus bicalutamide." (PMID 22956944, 2012). "In summary, the kava root extract and flavokawain B inhibited tumor growth in clinically relevant xenograft models, decreased AR expression in tumor tissues, and lowered serum PSA levels in tumor-bearing mice." (PMID 22347450, 2012). "Dihydrotestosterone supplementation partially restored tumor formation to androgen receptor knockout mice." (PMID 23284679, 2012). "In this report, the ligand-dependent dominant-negative ARΔ142–337 (ARΔTR) was expressed in castration-recurrent CWR-R1 cell and tumor models to elucidate the role of AR signaling." (PMID 22272301, 2012). "LacZ or ARΔTR-transduced cells were injected into nude mice to generate CWR-R1 tumors to assess the impact of ARΔTR on tumor growth and endogenous AR signaling." (PMID 22272301, 2012). "In castration-resistant prostate cancer (CRPC), AR activity remains critical for tumor growth despite androgen deprivation." (PMID 23019221, 2012). "A high level of FOXA1 was previously found in 89% of metastatic PC and the expression of FOXA1 was positively correlated with tumor size, extraprostatic invasion, AR and lymph node invasion." (PMID 22879989, 2012). "In a pilot study of patients receiving taxane chemotherapy, examination of AR nuclear localization and microtubule integrity in CTCs isolated using the CellSearch Circulating Tumor Cell Test device correlated with response to therapy." (PMID 23087897, 2012). "Both AR antagonists effectively inhibited tumor growth and reduced PSA levels throughout the study (P < 0.001)." (PMID 22849360, 2012). "In contrast, assessing somatic alterations in androgen-AR axis genes is more challenging, because this requires direct sampling of tumor tissue or tumor-derived cells." (PMID 22956944, 2012). "Single agent blockade of either the AR or mTOR pathway showed comparable levels of tumor response; however the combination treatment regimen (based on the clinical dosing schedules for each) resulted in virtually complete inhibition of tumor growth." (PMID 22614157, 2012). "The AR-antagonists were also evaluated for their in vivo efficacy in castrated VCaP tumor-bearing-CB17/lcr-Prkdc SCID mice treated with 25 mg/kg of Compound 30 and 100 mg/kg of Compound 26 daily by oral gavage." (PMID 22849360, 2012). "Amplification of the AR gene has been reported in 30% of tumour samples and is often accompanied by an increase in AR stabilization." (PMID 22548055, 2012). "Overall, the results presented here demonstrate inhibition of the CWR-R1 tumor growth by dominant negative inhibition of AR signaling, and indicate the central role of tumor-derived androgens in the development of castration-resistant CaP." (PMID 22272301, 2012). "Kava extract and flavokawain B treatment of mice with patient-derived xenografts reduced tumor growth and expression of AR and its target genes in tumor tissues, and lowered serum PSA levels." (PMID 22347450, 2012). "The CAG repeat lengths and AR expression was analyzed in relation to clinical, pathological, and biochemical features such as age, stage of disease, tumor size, lymph node involvement, histological grade, and sex hormone receptor expression." (PMID 23272232, 2012). "During the initial stage of CaP, the large majority of tumors are androgen dependent and responsive; furthermore, the AR signaling pathway plays an important role in tumor development and is important throughout progression." (PMID 22957009, 2012). "In the CWR-R1-LacZ tumors, intratumoral T and DHT levels were sufficient to activate AR-H874Y and promote tumor growth." (PMID 22272301, 2012).
tumor (continued). "Tissue levels of 0.32 nM DHT (p = 0.59) and 0.05 nM androsterone (p = 0.23) measured at the time of tumor harvest were similar in ARΔTR and LacZ-transduced tumors and sufficient to activate endogenous AR and ARΔTR (see in vitro results)." (PMID 22272301, 2012). "While the concept of androgen-receptor antagonism is not a novel concept, MDV3100 is notable for its extremely high receptor-binding affinity, ability to induce tumor cell apoptosis and pure androgen receptor antagonism." (PMID 22110494, 2012). "Positive cell populations stained with phosphor-AMPK or phosphor-ACC were significantly increased, while AR-positive cells were reduced in the B-DIM treated tumor tissue." (PMID 23056607, 2012). "The kava root extract and flavokawain B reduce tumor growth, AR expression in tumor tissues and levels of serum PSA in the patient-derived PCa xenograft models." (PMID 22347450, 2012). "Integration of sequence analysis, transcriptome profiling, cell viability assays and xenograft tumor growth inhibition studies enabled us to establish a direct cistrome-activity relationship for two novel potent AR antagonists." (PMID 22849360, 2012). "Despite this difference, both tumours from men and women express the androgen receptor, and exhibit a proliferative rate that is responsive to testosterone." (PMID 21468052, 2011). "The higher level of expression of the androgen receptor in tumours from male patients and the greater responsiveness to testosterone in tumours from men suggests that the larger size of tumours in male mice is related to this responsiveness." (PMID 21468052, 2011). "This metastasis originated from the LHSR TMPRSS2/ERG primary tumor, as it stained positive with human-specific anti-AR antibody." (PMID 21747944, 2011). "Immunohistochemical approaches to differentiate between these entities included the expression of androgen receptor, CD34, bcl-2, TGF-[beta], CD10, and staining for tumor-associated Merkel cells." (PMID 21152127, 2011). "AR overexpression decreases adhesion, invasion, and migration ability of ARCaP cells in vitro, as well as reduces ARCaP tumor growth in athymic mice." (PMID 21859492, 2011). "In another phase 1/2 study of men with CRPC without metastases, MDV3100 demonstrated antitumor activity in men both with and without prior chemotherapy exposure, validating the importance of continued AR signaling in tumor growth for men with CRPC." (PMID 21513551, 2011). "There was a significantly higher level of androgen receptor mRNA level in the tumours from males compared with tumours from females." (PMID 21468052, 2011). "Advanced-stage cancer cells, which continue to express the androgen receptor in a majority of tumor specimens, are resistant to apoptosis from androgen ablation or from the cytotoxicity induced by chemotherapeutic agents." (PMID 21276246, 2011). "In this study, AR diplotypes were analysed in relation to patient and tumour characteristics, endocrine treatment, and disease-free survival." (PMID 22033271, 2011). "AR expression analysis was not included in the routine analyses, and we were therefore unable to compare AR diplotype data with AR expression levels in the tumour." (PMID 22033271, 2011). "PLum-C tumors regressed in response to androgen deprivation, consistent with an AR+ luminal phenotype for the majority of tumor cells." (PMID 22022528, 2011). "In fact, the raise in serum PSA levels during relapse rather reflects the expansion of the tumor burden than increased AR activity in the tumor tissue self." (PMID 21829708, 2011). "ADT has been designed to eradicate cancer cells within a tumor by targeting the AR positive population." (PMID 24212771, 2011). "Although circulating levels of androgens are depleted in CRPC, tumor progression is often concomitant with elevated levels of the androgen receptor (AR), activation of the AR, and the expression of AR-regulated genes." (PMID 22114732, 2011).